IDUA (alpha-L-iduronidase)
Diseases named in the same sentence as IDUA in open-access papers (continued):
Sharing a sentence is not in itself a finding about the gene and the disease.
mucopolysaccharidosis type 1 (continued). "The mucopolysaccharidosis type I (MPS I) is a lysosomal storage disease resulting from the defective activity of the enzyme α-L-iduronidase (IDUA)." (PMID 29843745, 2018). "Mucopolysaccharidosis type I (MPS I; OMIM 252800) is an autosomal recessive lysosomal storage disease (LSD) caused by deficient activity of alpha-L-iduronidase (IDUA, EC 3.2.1.76)." (PMID 28859139, 2017). "Mucopolysaccharidosis type I (MPS I), known as Hurler syndrome [OMIM, #607014], is caused by a deficiency of IDUA lysosomal enzyme, and is inherited as autosomal recessive disease." (PMID 26407983, 2015). "Cumulatively, our results allow transition to pre-clinical studies of SB-mediated alpha-L-iduronidase expression and correction of mucopolysaccharidosis type I in animal models." (PMID 24205141, 2013). "Mucopolysaccharidosis I (MPSI) is a LSD in which two GAGs, dermatan and heparan sulfate, accumulate due to a deficiency in alpha-L iduronidase (IDUA - EC 3.2.1.76)." (PMID 22520214, 2012). "Mucopolysaccharidosis type I (MPS I) was a group of rare autosomal recessive disorder caused by the deficiency of the lysosomal enzyme, alpha -L -iduronidase, and the resulting accumulation of undergraded dematan sulfate and heparan sulfate." (PMID 22074387, 2011). "Mucopolysaccharidosis type I (MPS I) is an autosomal storage disease resulting from defective activity of the enzyme α-L-iduronidase (IDUA)." (PMID 21639919, 2011). "The main cause of mucopolysaccharidosis type I (Hurler syndrome OMIM #607014, Scheie syndrome OMIM #607016, Hurler-Scheie syndrome OMIM #607015) is a mutation in the α-L-iduronidase (IDUA) gene, which results in a deficiency or relative deficiency of the α-L-iduronidase enzyme." (PMID 38425718, 2024). "Other human AEC transplantation studies achieved reduced liver fibrosis in CCl4-treated immunocompetent C57BL/6 mice or restored the glycosaminoglycan (GAG)-degrading enzyme α-l-iduronidase (IDUA) function in the livers of mucopolysaccharidosis type 1 (MPS1) NOD.129(B6)-Prkdcscid Iduatm1Clk mice." (PMID 36831196, 2023). "Mucopolysaccharidosis Type I (MPS I) is a lysosomal storage disorder caused by a disfunction of α-L-iduronidase (IDUA), a lysosomal hydrolase coded by the IDUA gene, responsible for degrading two specific glycosaminoglycans (GAGs): heparan sulphate (HS) and dermatan sulphate (DS)." (PMID 31834922, 2019). "Hurler–Scheie syndrome is an intermediate form of mucopolysaccharidosis type I which is a rare lysosomal storage disorder caused by the deficiency or complete absence of enzyme alpha-L-iduronidase activity." (PMID 31018863, 2019). "Mucopolysaccharidosis I (MPS I) is an autosomal recessive lysosomal storage disorder caused by a lack of the lysosomal enzyme α-L-iduronidase (IDUA)." (PMID 27520059, 2016). "The Sleeping Beauty transposon system, a non-viral, integrating vector that can deliver the alpha-L-iduronidase-encoding gene, is efficient in correcting mucopolysaccharidosis type I in NOD/SCID mice." (PMID 24205141, 2013). "Mucopolysaccharidosis type I (MPS I) is inherited in an autosomal-recessive fashion and caused by deficiency of α-L-iduronidase (IDUA; EC 3.2.1.76) activity and progressive accumulation of its substrates, partially degraded dermatan and heparin sulfate, in lysosomes." (PMID 24053568, 2013). "Mucopolysaccharidosis type I (MPS I), an inherited lysosomal storage disorder characterized by deficiency of α-l-iduronidase (IDUA) activity, causes multisystemic pathology due to sequelae of accumulated heparan and dermatan sulfates (HS and DS), the substrates of IDUA." (PMID 40881820, 2023). "Indeed, Pompe disease (due to a deficiency of acid alpha-1,4-glucosidase, GAA) and mucopolysaccharidosis type I (MPS I, due to a deficiency of alpha-L-iduronidase, IDUA) have already been added to the US Secretary of Health and Human Services’ Recommended Uniform Screening Panel (RUSP)." (PMID 32802993, 2020).
mucopolysaccharidosis type 1 (continued). "Hurler–Scheie syndrome is an intermediate form of mucopolysaccharidosis type I (MPS I) which is a rare autosomal recessive lysosomal storage disorder caused by mutations in the alpha-L-iduronidase gene, responsible for a deficiency or complete absence of enzyme alpha-L-iduronidase activity." (PMID 31018863, 2019). "IDUA is the replacement enzyme for mucopolysaccharidosis type I (MPS I, also called Hurler, Hurler-Scheie Syndrome) and is responsible for degrading glycosaminoglycans (GAG; e.g., heparan sulfate and dermatan sulfate)." (PMID 26382970, 2015). "Galsulfase, indicated for Maroteaux-Lamy syndrome (MPS VI), addresses the deficiency of arylsulfatase B; laronidase, used for Hurler, Hurler-Scheie, and Scheie syndromes (MPS I), replaces the enzyme alpha-L-iduronidase." (PMID 40510111, 2025). "Mucopolysaccharidosis type I (MPS I), also called Hurler syndrome, is an autosomal recessive disorder characterized by inability to degrade glycosaminoglycan (GAG) owing to a deficiency of alpha-L-iduronidase (IDUA)." (PMID 28595620, 2017). "Iduronidase (IDUA) enzyme can be used for the treatment of mucopolysaccharidosis type I (MPSI) though it does not cross the BBB." (PMID 29843371, 2018). "Severe mucopolysaccharidosis type I, Hurler’s syndrome (MPS-IH), is a lysosomal storage disease due to mutations in the IDUA gene resulting in decreased/absent alpha-L-iduronidase activity." (PMID 27910891, 2016). "Mucopolysaccharidosis type I (MPS I) is a chronic, progressive, multisystemic lysosomal disease caused by a deficiency or absence of activity of the α-L-iduronidase (IDUA) enzyme." (PMID 21637564, 2010).
lysosomal storage disorder (36 papers, 2009 to 2025). "Pompe disease and Mucopolysaccharidoses Type I (MPS-I) are lysosomal disorders caused by a deficiency of α-glucosidase and alpha-L-iduronidase, respectively." (PMID 41272769, 2025). "Mucopolysaccharidosis type I (MPS I), is an autosomal recessive lysosomal storage disease caused by a deficiency of α-L-iduronidase (IDUA, EC 3.2.1.76) due to mutations in the IDUA gene, and affects ~ 1–9:1,000,000 live births." (PMID 41353341, 2025). "For example, in lysosomal storage disorders such as Hurler syndrome, rWGS can pinpoint mutations in the IDUA gene, enabling the development of CRISPR-based therapies to correct the underlying defect." (PMID 41404425, 2025). "Hurler syndrome, or MPS I, is a severe lysosomal storage disorder caused by mutations in the IDUA gene, which encodes the enzyme alpha-L-iduronidase." (PMID 39286678, 2024). "The phenotype observed in MPS IIIC cells can be compared with mucopolysaccharidosis type I (MPS I), a lysosomal storage disease caused by a mutation in the Idua gene, which codes α-L-iduronidase (IDUA)." (PMID 37756356, 2023). "Hurler Syndrome, a lysosomal storage disorder caused by deficiency of the enzyme alpha-L-iduronidase (IDUA) is the most commonly transplanted inherited metabolic disorder." (PMID 32903736, 2020). "Mucopolysaccharidosis (MPS) type-IH is a lysosomal storage disease that results from mutations in the IDUA gene causing the accumulation of glycosaminoglycans (GAGs)." (PMID 27910891, 2016). "Mucopolysaccharidosis1 (MPS1) is an autosomal recessive lysosomal storage disorder caused by null or nonsense mutations in the gene encoding alpha-L-iduronidase (IDUA), a ubiquitous intracellular and secreted enzyme that breaks down glycosaminoglycans (GAGs)." (PMID 26899286, 2016). "Mucopolysaccharidosis (MPS) I is a lysosomal storage disease caused by a deficiency of α-L-iduronidase (IDUA) (EC 3.2.1.76); enzyme replacement therapy is the conventional treatment for this genetic disease." (PMID 23898885, 2013). "Also known as gargoylism, this condition is a lysosomal storage disease caused by defects in the enzyme alpha-L-iduronidase, encoded by the IDUA gene on chromosome 4p16." (PMID 39846623, 2025). "Mucopolysaccharidosis type I (MPS I) is a lysosomal storage disorder (LSD) caused by mutations in the IDUA gene coding for the enzyme α-l-Iduronidase (IDUA) involved in the degradation of glycosaminoglycans (GAGs), such as heparan sulfate (HS) and dermatan sulfate (DS) in lysosome." (PMID 35893292, 2022). "MPS I-H is an autosomal recessive, lysosomal storage disease caused by mutations in the IDUA gene that leads to a severe deficiency of α-L-iduronidase, an enzyme that participates in the breakdown of the glycosaminoglycans (GAGs) dermatan sulfate and heparan sulfate." (PMID 35857082, 2022). "Mucopolysaccharidosis type I (MPS I; OMIM #252800) is a rare autosomal recessive lysosomal storage disorder caused by a deficiency in the alpha-L-iduronidase (IDUA) enzyme, which is involved in the breakdown of the glycosaminoglycans (GAGs) heparan sulfate and dermatan sulfate." (PMID 22524701, 2012). "Pseudodeficiency variants were also identified in other lysosomal storage disorders, such as p.R247W and p.R249W in the HEXA gene, p.A300T in the IDUA gene, p.R595W in the GLB1 gene, p.D152N in the GUSB gene, and p.D313Y in the GLA gene." (PMID 40449593, 2025). "Mucopolysaccharidosis type I S (MPS IS) is a rare autosomal recessive lysosomal storage disorder caused by mutations in the IDUA gene, leading to a deficiency of the enzyme alpha-L-iduronidase." (PMID 36052356, 2022).
Hurler syndrome (32 papers, 2012 to 2026). Hurler syndrome is the most severe form of mucopolysaccharidosis type 1 (MPS1), a rare lysosomal storage disease, characterized by skeletal abnormalities, cognitive impairment, heart disease, respiratory problems, enlarged liver and spleen, characteristic facies and reduced life expectancy. "Herein, we report two cases of Hurler Syndrome with a recurrent homozygous variant in the IDUA gene, c.1045G>T." (PMID 41226457, 2025). "This case report details a 12-year-old male diagnosed with Hurler syndrome, a rare autosomal recessive disorder caused by a deficiency in the enzyme alpha-L-iduronidase." (PMID 39286678, 2024). "The pathophysiology of Hurler syndrome is closely linked to the deficiency of alpha-L-iduronidase, which is essential for the breakdown of dermatan sulfate and heparan sulfate, two major types of GAGs." (PMID 39286678, 2024). "One cause of Hurler syndrome is due to the presence of a premature stop codon in exon 9 of the IDUA gene, which prevents the production of functional IDUA protein." (PMID 39080265, 2024). "Stem cell transplant (SCT) with MSCs is a primary form of treatment of infants with MPSI or Hurler syndrome, which is caused by mutations in the IDUA gene." (PMID 35745855, 2022). "Mucopolysaccharidosis (MPS) Type I (MPSI), also called Hurler syndrome, is caused by mutations in the gene encoding the lysosomal enzyme, α-L-iduronidase (IDUA)." (PMID 35745855, 2022). "Here we tested three different human transgenes encoding for: α-L-iduronidase (IDUA; Hurler syndrome, OMIM #607014), α-galactosidase (GLA; Fabry disease, OMIM #301500) and lysosomal acid lipase (LAL; Wolman disease, OMIM #278000)." (PMID 32728076, 2020). "In 1968, Fratantoni reported that co-culture of wildtype skin fibroblasts with mutant fibroblasts from patients with alpha-L-iduronidase deficiency (Hurler syndrome) rescued the metabolic defect." (PMID 22912749, 2012). "Specific enzyme assays were conducted to rule out these conditions by confirming the absence of the enzyme deficiencies characteristic of these other mucopolysaccharidoses and verifying the deficiency in alpha-L-iduronidase, thereby confirming the diagnosis of Hurler syndrome." (PMID 39286678, 2024). "Hurler syndrome (OMIM # 219700) is one of the mucopolysaccharidoses caused by homozygous or compound heterozygous mutations in the IDUA gene encoding alpha-L-iduronidase, a lysosomal enzyme participating in the degradation of dermatan sulfate and heparan sulfate." (PMID 38959711, 2024). "This phenotype was confirmed by elevated urinary GAGs (HS 121.9 mg/mMol creatinine, nv < 4.6; DS 80.0 mg/mMol creatinine, nv < 38.1); genetic analysis of the IDUA gene revealed compound heterozygosity for two known pathogenic mutations (c.46–57del12/p.Y201X) consistent with Hurler syndrome." (PMID 33147872, 2020). "Some Hurler Syndrome patients, suffering from skeletal abnormalities and cognitive impairment, carry a nonsense mutation in the IDUA gene that prevents the production of a functional full-length IDUA protein in these patients." (PMID 32575694, 2020). "In addition, Fahiminiya S and colleague studied consanguineous families in Qatar and indicated a SNP‐causing Hurler syndrome in IDUA gene using whole exome sequencing." (PMID 31386236, 2019). "In MPS I mice (a model of Hurler disease caused by alpha-L-iduronidase deficiency) both HS and DS accumulate and the mice have similar changes in microglial activation genes as MPS IIIb; however, genes associated with inflammation are not up-regulated (e.g. Ifitm1, Ifnar2 )." (PMID 22403656, 2012). "In addition, when AAV-delivered circular arRNAs are systematically administered to a humanized mouse model of Hurler syndrome, it rectifies the premature stop codon precisely and restores the functionality of IDUA enzyme encoded by the Hurler causative gene in multiple organs." (PMID 37872590, 2023).
Hurler syndrome (continued). "Hurler syndrome is a rare autosomal recessive disorder of deficiency in the metabolism of glycosaminoglycans (GAGs), including heparan sulfate and dermatan sulfate, which consequently accumulate in the different organs of the body, resulting from deficiency of an enzyme named Alpha-L-iduronidase." (PMID 37213966, 2023). "Hurler syndrome, or MPS type I, is caused by a deficiency in α-L-Iduronidase (encoded by the IDUA gene), leading to the pathological storage of dermatan- and heparan- sulfate inside the lysosomes of a wide range of tissues." (PMID 41511290, 2025). "Hurler syndrome (MPS IH, OMIM #607014) is the most severe phenotype of MPS type I, reflecting absence or extremely low levels of IDUA enzymatic activity, associated with insertions/deletions, nonsense, splice variants, and missense variants in the IDUA gene." (PMID 38456506, 2024). "This thymine base editor (TBE) exhibits high editing specificity and significantly restores IDUA enzyme activity in cells derived from patients with Hurler syndrome." (PMID 39080265, 2024). "In Hurler syndrome, a monogenetic disease, CLUSTER was tested on mutated Alpha-L-iduronidase (IDUA)." (PMID 38203521, 2023). "Hurler Syndrome, the most severe phenotype of Mucopolysaccharidosis Type I (MPS IH), is characterized by loss of function variants of the IDUA gene, which encodes alpha-L-iduronidase." (PMID 35693884, 2022). "In our Hurler syndrome (HLS) (MPS I; α-L-Iduronidase deficiency) in vivo model, although the expression of the IDUA gene was not severely downregulated within the brain–midgut axis, reduced lifespan and locomotor deficiency were observed." (PMID 41511290, 2025). "Hurler’s syndrome (MPS-IH), which is the most severe form of MPS-I, appears to affect the pediatric age group, with extremely low levels or an absence of IDUA enzyme activity thought to be the cause." (PMID 40427026, 2025).
mucopolysaccharidosis (10 papers, 2012 to 2024). A group of autosomal recessive or X-linked inherited lysosomal storage disorders affecting the metabolism of mucopolysaccharides, resulting in the accumulation of mucopolysaccharides in the body. "Beyond sphingolipid/ceramide metabolism, our screen also identifies many fly homologs of genes causing human mucopolysaccharidoses (e.g., GLB1, IDS, IDUA, MAN2B1, MANBA)." (PMID 37200393, 2023). "Mucopolysaccharidosis, first described in 1919, is an autosomal recessive lysosomal disease of overload linked to the deficiency of an enzyme of GAG metabolism, IDUA." (PMID 35465368, 2022). "Mucopolysaccharidosis (MPS) Type I (MPSI) is caused by mutations in the gene encoding the lysosomal enzyme, α-L-iduronidase (IDUA), and a majority of patients present with severe neurodegeneration and cognitive impairment." (PMID 29976218, 2018). "Mucopolysaccharidosis (MPS) Type I (MPSI) can present as severe MPSI (Hurler syndrome) or attenuated MPSI (Hurler-Scheie, or Scheie syndrome), and is caused by mutations in the gene encoding the lysosomal enzyme α-L-iduronidase (IDUA)." (PMID 29976218, 2018). "One can speculate that the affected transcript is non-essential for the enzymatic function of IDUA that is disrupted in the IDUA-associated metabolic condition Mucopolysaccharidosis (OMIM #607014)." (PMID 36945502, 2023). "Mucopolysaccharidosis I is caused by a deficiency of α-L-iduronidase (IDUA; EC 3.2.1.76) and can result in a wide range of phenotypic involvement with three major recognized clinical entities: Hurler (MPS IH; MIM#607014), Hurler-Scheie (MPS IH/S; MIM#607015), and Scheie (MPS IS) syndromes." (PMID 22013531, 2012).
Hurler-Scheie syndrome (6 papers, 2015 to 2023). Hurler-Scheie syndrome is the intermediate form of mucopolysaccharidosis type 1 (MPS1) between the two extremes Hurler syndrome and Scheie syndrome ; it is a rare lysosomal storage disease, characterized by skeletal deformities and a delay in motor development. "The clinical history, radiological abnormalities of the skeleton, and deficiency of enzyme alpha-L-iduronidase allowed us to consider in our patients the diagnosis of the intermediate form of MPS I (Hurler–Scheie syndrome)." (PMID 31018863, 2019). "The diagnosis of Hurler–Scheie syndrome was considered in these patients on the basis of clinical and radiological arguments, with the highlighting of a deficiency of enzyme alpha-L-iduronidase in serum and leukocytes." (PMID 31018863, 2019). "A number of mutations in IDUA, which cause MPS I (Hurler, Scheie, and Hurler-Scheie syndromes), are apt targets for base editors." (PMID 31248000, 2019).
Cognitive impairment (3 papers, 2018 to 2024). Abnormal cognition is characterized by deficits in thinking, reasoning, or remembering. "Notably, the cognitive impairments in our patient were milder than typically observed, which may suggest variability in the expression of the disease or differences in the residual activity of alpha-L-iduronidase." (PMID 39286678, 2024).
Fabry disease (2 papers, 2020). Fabry disease (FD) is a progressive, inherited, multisystemic lysosomal storage disease characterized by specific neurological, cutaneous, renal, cardiovascular, cochleo-vestibular and cerebrovascular manifestations. "Using this method, they were able to produce supraphysiologic levels of several proteins, including alfa-galactosidase A (the enzyme deficient in Fabry disease), factor IX (hemophilia), and alpha-L-iduronidase (or IDUA, the enzyme deficient in MPSI)." (PMID 31941077, 2020).
Gaucher disease (2 papers, 2022 to 2026). Gaucher disease (GD) is a lysosomal storage disorder encompassing three main forms (types 1, 2 and 3), a fetal form and a variant with cardiac involvement (Gaucher disease - ophthalmoplegia - cardiovascular calcification or Gaucher-like disease). "ABG, ASM, GALC, IDUA, and GAA are lysosomal enzymes with reduced activity in Gaucher disease, Nimann-Pick disease, Krabbe disease, MPS-I, and Pompe disease, respectively." (PMID 35419325, 2022).
Krabbe disease (2 papers, 2020 to 2022). A lysosomal disorder that affects the white matter of the central and peripheral nervous systems. "For example, chloramphenicol has been shown to enhance alpha-L-iduronidase (IDUA) activity in cell lines of MPS I patients, whereas ataluren has shown effects on the galactocerebrosidase activity in Krabbe disease (KB) mice and on palmitoyl-protein thioesterase 1 activity in NCL mice." (PMID 32722587, 2020).
metastatic disease (2 papers, 2019 to 2021). "IDUA(Iduronidase, Alpha-L) is associated with visceral organ metastatic disease in breast cancer." (PMID 33790307, 2021).